ENSG00000288550 (novel protein)
Gene: Protein-coding gene on chromosome 3 (9,917,116 to 9,945,385, forward strand). Ensembl gene ENSG00000288550.
Genetic constraint (gnomAD): Missense variants: 560 observed, 621.16 expected, observed/expected ratio (o/e) 0.9, 90% interval 0.84 to 0.97. Synonymous variants: 250 observed, 259.22 expected, observed/expected ratio (o/e) 0.96, 90% interval 0.87 to 1.07.